IL24 (interleukin 24)
Diseases named in the same sentence as IL24 in open-access papers (continued):
Sharing a sentence is not in itself a finding about the gene and the disease.
cancer (continued). "The combination of IL‐24 and immune checkpoint inhibitors has recently gained importance in the field of cancer treatment." (PMID 40338095, 2025). "While IL-24-based therapies have progressed to phase I/II clinical trials for various advanced cancers (ClinicalTrials.gov Identifier: NCT00116363), significant advancements in clinical outcomes have yet to be achieved." (PMID 40866941, 2025). "Despite its therapeutic importance, Lithium remains the only FDA-approved GSK3β inhibitor, underscoring the potential of IL-24 as an anti-cancer agent explored in this study." (PMID 40072085, 2025). "The molecular mechanism driving the anti‐cancer activity of IL‐24 seems to vary depending on the specific cancer model under investigation." (PMID 40338095, 2025). "Further research into the interactions between TXNIP, CAST, and IL-24 is essential to better understand their roles in cancer." (PMID 40175348, 2025). "The strategic utilization of IL-24 in cancer therapy leads to a promising method of precision medicine, navigating toward an effective approach in cancer treatment." (PMID 40661937, 2025). "The integration of NKG2D and IL24 within NK-Exos confers a dual therapeutic mechanism, synergistically amplifying their efficacy in cancer treatment." (PMID 40076725, 2025). "Lastly, the complex roles of CAST and IL-24 in cancer underscore the need for more comprehensive studies to fully understand the diverse effects and therapeutic potential of these molecules." (PMID 40175348, 2025). "To better understand the mechanism by which IL-24 induces apoptosis, we analyzed the role of glycogen synthase kinase-3 beta (GSK3β), a highly conserved serine/threonine kinase in cancer cells and a downstream target of PKA." (PMID 40072085, 2025). "Unraveling the biochemical basis of IL-24’s cancer-selective activity is a key to unlocking this molecule’s potential to enhance cancer treatments." (PMID 40072085, 2025). "Understanding the biology of IL‐24 in relevance to cancer progression has become a focal point of research." (PMID 40338095, 2025). "This review focuses on providing an overview of recent progress in understanding the biology of IL‐24 and its downstream signaling and its utilization as a therapeutic tool for cancer management and other human diseases." (PMID 40338095, 2025). "These examples illustrate the various mechanisms by which IL‐24 regulates apoptosis in different cancer models." (PMID 40338095, 2025). "The work reported here provides direct evidence that inhibiting GSK3β activity with IL-24 induces apoptosis in cancer cells." (PMID 40072085, 2025). "Future studies should precisely delineate the most effective combinations of IL-24 as a GSK3β inhibitor with cytotoxic agents for prostate and other cancers." (PMID 40072085, 2025). "This study shows, for the first time, that the molecular mechanism of the cancer-specific killing effect observed in IL-24-treated cells involves a GSK3β-dependent pathway." (PMID 40072085, 2025). "The discovery of interleukin (IL)‐24 and studying its biological activity demonstrate its potential to serve as a therapeutic for human diseases, especially for cancer treatment." (PMID 40338095, 2025). "Building on these initial reports, multiple laboratories, including our own, have investigated IL‐24 as a potential cancer treatment for various human cancer models, both in vitro and in vivo." (PMID 40338095, 2025). "In summary, the multifunctional cytokine IL‐24 has gained clinical relevance in the field of cancer." (PMID 40338095, 2025). "Since no prior study had established a link between TXNIP and IL-24 in cancer development, we conducted further validation and functional assays of IL-24 due to its recognized role in cancer-specific cytotoxicity." (PMID 40175348, 2025). "IL24 selectively induces apoptosis in cancer cells, sparing normal cells, making it an appealing therapeutic candidate." (PMID 39850884, 2024).
cancer (continued). "The antitumor activity of interleukin-24 (IL-24), a unique cytokine cancer suppressor gene in the IL-10 cytokine family, has been demonstrated in a variety of tumors." (PMID 38711526, 2024). "Interleukin-24 (IL-24) is a cytokine with potential antitumor effects that can affect a wide range of cancers." (PMID 39456230, 2024). "IL24 is involved in various biological processes, primarily known for its roles in immune response and cancer biology." (PMID 39850884, 2024). "Previous studies have reported that ectopic expression of IL24 can selectively terminate cancer cells with little, if any, effect on normal cells." (PMID 38414326, 2024). "One study evaluated the possible role of IL-24, a member of the IL-10 family, in inhibiting cancer pain." (PMID 38940936, 2024). "The interaction of IL-24 with σ1 in the endoplasmic reticulum and the induction of ER stress are essential for cancer-specific apoptosis." (PMID 37444474, 2023). "Inherent biochemical differences between normal and cancer cells lead to different responses to IL-24." (PMID 37280571, 2023). "According to previous research, the Mda-7/IL-24 protein promotes apoptosis in cancer cells in a way comparable to that of endogenously produced protein." (PMID 37280571, 2023). "We have shown that IL-24 interacts with σ1 and that interaction is a critical upstream signal for IL-24-induced apoptosis in cancer cells." (PMID 37444474, 2023). "Further experiments are needed to determine if SOCS protein plays a role in IL-24-dependent cancer apoptosis." (PMID 37444474, 2023). "Studies by us and others have demonstrated the activation of multiple signaling pathways by IL-24 in a spectrum of cancer cells resulting in the activation of the caspase cascade and induction of apoptosis." (PMID 37280571, 2023). "In this article, we have investigated the use of health-promoting bacteria as a gene delivery system (IL-24 gene) for cancer therapy in vivo." (PMID 35814447, 2022). "Previously, several studies reported that IL-24 selectively induced growth arrest in cancer cells but had minimal effects on normal cells, and this evidence supported our data." (PMID 36100847, 2022). "IL19 can directly influence immune cells, IL20 has a significant effect on skin inflammation, and IL24 can promote apoptosis of different types of cancer." (PMID 35883015, 2022). "MDA-7/IL-24 inhibits the proliferation of cancer cells and of the engineered molecules tested, M7S maximally inhibited growth as measured by MTT assays." (PMID 35402258, 2022). "Interleukin-24 (IL-24) is a novel tumor suppressor cytokine that can selectively induce cancer cell apoptosis, and it has been utilized as a cancer gene therapy strategy." (PMID 35292065, 2022). "The introduction of immune-promoting genes such as GM-CSF can stimulate immune responses against tumors, and the delivery of TRAIL or IL-24 effectively eliminates cancer cells via apoptosis, playing crucial killing roles not only in CSCs but also in non-CSCs." (PMID 36146619, 2022). "Recent studies have shown that MDA-7/IL-24 controls several microRNAs, such as miR-221, that are upregulated in diverse types of cancer." (PMID 36146619, 2022). "IL-24 is a cytokine with a cancer cell-specific apoptosis-inducing effect; however, it lacks proper cell penetration ability." (PMID 35631493, 2022). "Previous studies have demonstrated that IL-24 can exert its cytotoxic effects on a broad spectrum of human cancers." (PMID 35292065, 2022). "The function of IL-24 in cancer cells was inconsistent with our finding in normal human bronchial epithelial cells." (PMID 36100847, 2022). "Flow cytometric analyses also indicated that VG9-IL-24 induced SMMC-7721 cell cycle arrest at the G2/M phase, which is consistent with results of other studies that have demonstrated that IL-24 can induce G2/M cell-cycle arrest in various cancer cell lines." (PMID 35292065, 2022).
cancer (continued). "To improve the delivery and therapeutic efficacy of MDA-7/IL-24 we created bipartite conditionally replicating adenoviruses expressing mda-7/IL-24, also known as a cancer terminator virus (CTVs)." (PMID 33670594, 2021). "Several previous reports also establish the use of MDA-7/ IL-24 and epigenetic therapeutics as a combination treatment against cancer." (PMID 35008495, 2021). "This activity is displayed by both normal and cancer cells, while only the cancer cells die when mda-7/IL-24 is expressed." (PMID 35008495, 2021). "Neutralizing anti-IL-24 antibody inhibited the anti-cancer activity of IL-24, which was earlier induced by Hiltonol treatment." (PMID 33562773, 2021). "This review summarizes the history and our current understanding of the molecular/biological mechanisms of MDA-7/IL-24 action rendering it a potent cancer suppressor." (PMID 35008495, 2021). "In many cancers, mda-7/IL-24 enhances pro-apoptotic and decreases anti-apoptotic Bcl-2 family member protein expression and elevates ER stress-related protein expression." (PMID 33670594, 2021). "A key element in MDA-7/IL-24’s effectiveness as an anticancer agent is its ability to be secreted by both normal and cancer cells resulting distinctively in the killing of primary and distant (metastatic) cancer cells." (PMID 33670594, 2021). "Ceramide is an important component in MDA7/IL-24-mediated induction of cancer cell-specific apoptosis." (PMID 35008495, 2021). "Although mda-7/IL-24 has consistently proven efficient in inducing antitumor effects in multiple types of cancers when delivered by Ads." (PMID 35008495, 2021). "mda-7/IL-24 induces potent anti-invasion and anti-metastasis activities in cancers of the cervix, lung, liver and prostate." (PMID 35008495, 2021). "mda-7/IL-24 incorporated in ZD55-IL-24 (an oncolytic adenovirus) was used in combination with cisplatin in a panel of cancer cells and the combination treatment markedly enhanced the cytotoxicity and apoptosis in all of the cancer cells tested." (PMID 35008495, 2021). "Interleukin 24 (IL‐24) is an IL‐10 family member and a secreted cytokine characterized by cancer‐targeted toxicity and can activate apoptosis by sensitizing cancer cells to chemotherapy." (PMID 33274495, 2021). "Several research groups have established that MDA-7/IL-24 can radiosensitize a diverse array of cancer cell lines both in vitro and in vivo." (PMID 35008495, 2021). "The CTV produces selective cancer destruction through cytolysis (promoted by viral replication) and by the multiple mechanisms in which mda-7/IL-24 can eliminate cancer cells." (PMID 33670594, 2021). "In this review, we review specific aspects of MDA-7/IL-24 function including its anti-cancer properties, combinatorial effects with other agents, early Phase I clinical trial and future prospects." (PMID 35008495, 2021). "MDA-7/IL-24 promotes cancer-selective apoptosis by inducing endoplasmic reticulum (ER) stress, which causes up-regulation of BiP/GRP78, induction of pro-apoptotic proteins (such as BAX), and repression of anti-apoptotic proteins (such as BCL-2)." (PMID 33670594, 2021). "Accordingly, Carmofur (an acid ceramidase inhibitor) promotes ceramidase accumulation in cells after MDA-7/IL-24 treatment inducing cancer-specific apoptosis." (PMID 35008495, 2021). "Recent studies have shown MDA‐7/IL‐24 to control many microRNAs, such as miR‐221, which is upregulated in many types of cancer." (PMID 33274495, 2021). "Another attribute of MDA-7/IL-24 is its ability to synergize with radiation, chemotherapy, antibody and/or immune therapy approaches resulting in enhanced eradication of cancer cells." (PMID 33670594, 2021). "These traits establish MDA-7/IL-24 as one of the most promising therapeutic cytokines in the cancer research field." (PMID 35008495, 2021).
cancer (continued). "Several research laboratories in the USA and globally have studied the biological functions and molecular mechanisms of MDA-7/IL-24 for more than two decades, which has enriched our understanding about the multiple functions of this potent cancer therapeutic." (PMID 35008495, 2021). "Previous studies confirmed that ectopic expression of mda-7/IL-24 induces endoplasmic reticulum (ER) stress and apoptosis in a wide array of cancer cells through modulation of relevant signaling pathway molecules." (PMID 33670594, 2021). "The future of MDA-7/IL-24 combination treatments is rife with opportunities that need to be explored further, based on its multidimensional therapeutic ability and cancer cell-specific killing properties." (PMID 35008495, 2021). "The majority of studies have utilized a replication incompetent Ad expressing mda-7/IL-24 (Ad.mda-7) for delivering MDA-7/IL-24 to cancer cells." (PMID 35008495, 2021). "These profound results with CTV and other CRCAs expressing mda-7/IL-24 support their use as a potential therapeutic for diverse cancer indications." (PMID 35008495, 2021). "Other ROS generating therapeutic agents, including arsenic trioxide, 4-hydroxyphenyl-retinamide (4-HPR), have also been shown to augment the therapeutic effect of MDA-7/IL-24 in cancers of the pancreas and kidney." (PMID 35008495, 2021). "As an anti-cancer agent, MDA-7/IL-24 controls multiple types of tumors, by inducing apoptosis and toxic autophagy, anti-invasion, anti-angiogenesis, sensitizing cancer cells to radiation therapy and chemotherapy." (PMID 35008495, 2021). "IL-24-iPSCs is thought to be promising for the development of off-the-shelf therapeutic MSCs in cancer therapy." (PMID 32015693, 2020). "ZD55-IL-24 can infect, directly lyse, and express a large amount of exogenous IL-24 in human cancer cells within cancer patient’s tumors." (PMID 33257647, 2020). "On the one hand, different from those in the HD-MSCs group, AA-MSCs highly expressed proinflammatory and cancer-associated genes (IL1B, IL-24, CXCLs, FOS, KLK10)." (PMID 32054519, 2020). "Apart from many interleukins, IL-24 is known as a multifunctional cancer killing interleukins, we found the expression of IL-24 was high in combination of PI-103 and EPZ-6438." (PMID 33473259, 2020). "The therapeutic gene engineered in this study was IL-24, a novel cancer growth-suppressing and apoptosis-inducing gene, which has been demonstrated efficient and safe in preclinical studies based on adenovirus 30-33." (PMID 31956348, 2020). "Previous studies have demonstrated that IL-24 is able to induce G2/M cell-cycle arrest in various cancer cell lines 12, 17-19." (PMID 31956348, 2020). "The body will be protected by regulating the expression of the IL24 mRNA as an immune factor during cancer." (PMID 33014054, 2020). "CD4+ and CD8+ T cells were purified from peripheral bloods and cancer specimens, and were stimulated with low (10 ng/ml) and high (100 ng/ml) concentration of recombinant IL-24." (PMID 31921658, 2019). "We confirmed previous studies showing that IL24 can trigger a certain amount of apoptosis in cancer cells." (PMID 31081251, 2019). "Comparative analysis between stably and transiently transfected IL-24 in cancer cells revealed similar inhibitory effects on GLI1 expression." (PMID 31783569, 2019). "In terms of IL-24 expression regulation in cancer cells, two studies have demonstrated that IL-24 mRNA regulation occurs at the 3’ untranslated region (3’UTR) end via activation of p38MAPK." (PMID 30669553, 2019). "Whilst IL-24 as a cancer therapeutic is accepted, its role on HH signaling and/or its downstream target GLI1 remains elusive." (PMID 31783569, 2019). "We show that an important direct target of HDAC7 is IL24, which is sufficient to suppress the growth of cancer stem‐like cells." (PMID 31081251, 2019). "It was well accepted that IL-24 mediated cancer cell-specific death and apoptosis via multiple signaling pathways." (PMID 31921658, 2019).
cancer (continued). "For instance, IL-24, a promising candidate for cancer gene therapy, preferentially inhibits growth and induces apoptosis in a variety of cancer cells without harming normal cells." (PMID 30643005, 2019). "While several in vitro and in vivo studies have characterized IL-24 as specific cancer killing protein in PCa cells compared to normal prostate epithelial cells, IL-24 expression in PCa, specifically in CRPC cells, is not fully understood." (PMID 30669553, 2019). "Based on this data we decided to elucidate the fate of internalized IL-20/IL-22 receptors in MDA-7/IL-24-stimulated cancer cells." (PMID 31489119, 2019). "Previous studies have shown that MDA-7/IL-24 induces apoptosis only in cancer cells that have a complete set of functional IL-20R/IL-22R receptor pairs, but cancer cells that lack a complete set of receptors can escape the MDA-7/IL-24 mediated cell death." (PMID 31489119, 2019). "Collectively, these data suggest that clathrin-dependent internalization of MDA-7/IL-24 is required for the cytokine signaling from and yet to be defined intracellular compartment of cancer cells." (PMID 31489119, 2019). "The evidence presented here points to PKA as a possible upstream regulator that potentiates IL-24 killing of cancer cells." (PMID 30424508, 2018). "Interleukin-24 (IL-24) is a member of the IL-10 protein family and it displays broad cancer-specific suppressor effects." (PMID 30424508, 2018). "The work reported here provides a previously unrecognized mode of inhibition of translation initiation whereby IL-24 inhibited eIF4A to induce apoptosis in cancer cells." (PMID 29786657, 2018). "Our data here provide strong evidence that Sigma 1 Receptor (Sig1R) is a critical upstream signal for IL-24-induced eIF4A down-regulation, the translation of mRNAs bearing long and structured 5′UTRs, mitochondrial dysfunction and apoptosis in cancer cells." (PMID 29786657, 2018). "IL-24 induces cancer cell death at high concentrations, triggers autoimmune responses, cardiovascular protection, inhibits keratinocyte growth, and possesses antibacterial activity." (PMID 29662489, 2018). "Our previous studies have shown that recombinant bioactive IL-24 protein as well as secreted IL-24 protein (generated from Ad.IL-24-infected cells) exerts cancer-specific killing through a mechanism identical to Ad.IL-24 infection." (PMID 29786657, 2018). "Consistently, overexpression of eIF4A conferred cancer cells with resistance to IL-24-induced cell death." (PMID 29786657, 2018). "We have demonstrated that Sig1R is the common upstream initial signal transduction molecule involved in IL-24-induced cancer-specific apoptosis." (PMID 29786657, 2018). "IL-24 exerts an antitumor effect by sensitizing transformed cell chemotherapy, facilitating cancer cells apoptosis, and hindering the process of angiogenesis." (PMID 29662489, 2018). "IL-24 has been evaluated as an anti-cancer molecule because cancer cells transfected with IL-24 exhibit inhibited cell growth and colony formation." (PMID 29330517, 2018). "Experimental studies with overexpression of IL-24 in cancer cell lines or studies, in which a small molecule stabilizes IL-24, suggested that IL-24 can potentially be used to enhance the efficacy of chemotherapies." (PMID 29967613, 2018). "We have determined that IL-24 action in cancer cells is mediated by an antagonistic effect of IL-24 on Sig1R." (PMID 29786657, 2018). "We have shown that IL-24 regulates apoptosis through phosphorylated eukaryotic initiation factor 2 alpha (eIF2α) during endoplasmic reticulum (ER) stress in cancer." (PMID 30424508, 2018).